PIGR (polymeric immunoglobulin receptor)
Diseases named in the same sentence as PIGR in open-access papers (continued):
Sharing a sentence is not in itself a finding about the gene and the disease.
Failure to thrive (1 paper, 2019). Failure to thrive (FTT) refers to a child whose physical growth is substantially below the norm. "The increased gut permeability seen in pIgR−/− animals is also observed in other diseases and conditions affecting the GIT, which present as significantly delayed growth or a failure to thrive." (PMID 30943912, 2019).
Fever (1 paper, 2024). Body temperature elevated above the normal range. "Furthermore, we found that fever‐cause categories showed the strongest correlation with PIGR (R = 0.47), SAA1 (R = 0.46), and SAA2 (R = 0.42), although no distinct pattern was discernible for fever‐cause." (PMID 39441646, 2024).
fibrosis (1 paper, 2021). the formation of excess fibrous connective tissue in an organ or tissue in a reparative or reactive process. "In addition, we saw two peptide fragments of the polymeric immunoglobulin receptor upregulated in the fibrosis group." (PMID 34287333, 2021).
gastritis (1 paper, 2013). Inflammation of the stomach. "Gastritis can also stimulate immunological activity in the human antrum, where abundant IgA-positive plasma cells were detected and pIgA was secreted by pIgR-expressing epithelium." (PMID 24236214, 2013).
Giardia infection (1 paper, 2019). "The transcription patterns of pIgR and RORγt were not impacted by the Giardia infection." (PMID 31222079, 2019).
Granuloma (1 paper, 2023). A compact, organized collection of mature mononuclear phagocytes, which may be but is not necessarily accompanied by accessory features such as necrosis. "Upon peritoneal immunization, we have demonstrated the pronounced affluence of IgT and the pIgR mRNA+ signal in the peritoneum, which is associated with vaccination adherences and granulomas." (PMID 37893915, 2023).
heart failure (1 paper, 2020). Inability of the heart to pump blood at an adequate rate to meet tissue metabolic requirements. "To investigate the association of pIgR peptides with cardiovascular diseases, we extracted additional urinary proteome data from the Human Urinary Database with respect to heart failure and CAD with patient information on the eGFR." (PMID 32427855, 2020). "The levels of pIgR peptides in patients with heart failure and CAD when compared with healthy controls are significantly increased." (PMID 32427855, 2020). "Furthermore, we were able to demonstrate that there is also an association of pIgR with CAD and heart failure." (PMID 32427855, 2020). "There was a significant positive correlation of albumin with pIgR peptides levels (rho = 0.277; p = 0.005) in the heart failure and CAD patients without CKD." (PMID 32427855, 2020).
inflammatory skin disease (1 paper, 2020). Inflammatory skin disorders covers a broad category that includes many conditions ranging in severity, from mild itching to grave medical health complications These disorders are common in people of all ages and races. "Previous studies have indicated that PIGR and its secretory component have an anti-inflammatory role in inflammatory skin diseases." (PMID 33178726, 2020).
Jaundice (1 paper, 2023). Yellow pigmentation of the skin due to bilirubin, which in turn is the result of increased bilirubin concentration in the bloodstream. "Tonack and collaborators have also looked for potential plasma biomarkers for PDAC and found some candidates, but they are associated with jaundice, showing the highest sensitivity of ITIH3, C5, A1BG, PIGR, and Reg3A in this condition." (PMID 37628784, 2023).
leukaemia (1 paper, 2021). "Accordingly, we found universal expression of the polymeric immunoglobulin receptor (pIgR) in HGSOC, as well as in tumour-free fallopian tube, ovarian and omental tissue (but not in THP1 monocytes or in K562 leukaemia cells)." (PMID 33536615, 2021).
liver failure (1 paper, 2021). A liver disease characterized by the liver losing or has lost all of its function. "In HBV infection, PIGR mRNA was significantly upregulated in HBV-associated liver failure samples compared to normal individuals and liver angioma in GSE38941 and GSE96851 (both p < 0.001)." (PMID 33937393, 2021).
lung fibrosis (1 paper, 2019). "Moreover, PIGR-deficient mice demonstrated attenuated lung fibrosis after bleomycin treatment compared with wild-type mice." (PMID 31640794, 2019).
malnutrition (1 paper, 2020). Inadequate nutrition resulting from poor diet, malabsorption, or abnormal nutrient distribution. "Moreover, it was shown that malnutrition altered B cell differentiation status in bone marrow, led to a predominance of plasma cells among small intestinal lamina propria lymphocytes, decreased polymeric immunoglobulin receptor expression, and reduced secretory IgA in mucosal sites." (PMID 32117313, 2020).
mastitis (1 paper, 2016). Inflammation of breast tissue during lactation or postpartum due to an obstructed duct or infection. "The tg bovine over-expression of pIgR could increase the SIgA in the mammary gland; it would provide stronger and longer protection against the mastitis pathogens from the environment." (PMID 27375616, 2016). "FcRn or pIgR over-expression in bovine could also be useful for the treatment of mastitis." (PMID 27375616, 2016).
melanoma (1 paper, 2020). A malignant, usually aggressive tumor composed of atypical, neoplastic melanocytes. "In our previous studies, we have found that expression of two SLN genes (PIGR and TFAP2A), when combined with clinicopathological features, correlated with prognosis in SLN-positive melanoma patients." (PMID 33373316, 2020).
metastatic tumours (1 paper, 2014). "PIGR expression in primary and metastatic tumours was rather similar, suggesting that downregulation of PIGR occurs early in ovarian carcinogenesis." (PMID 24568264, 2014).
Multiple Organ Failure (1 paper, 2025). A progressive condition usually characterized by combined failure of several organs such as the lungs, liver, kidney, along with some clotting mechanisms, usually postinjury or postoperative. "Among PIS subjects, only those with multiple organ failures (SOFA score > 12) had a significantly higher level of pIgR than CAP subjects (SOFA = 0)." (PMID 40642082, 2025).
Obesity (1 paper, 2025). Accumulation of substantial excess body fat. "Furthermore, the expression of 15 breast milk proteins, including the fragment of the sixth extracellular domain of the polymeric immunoglobulin receptor (PIGR), differed between mothers with and without obesity." (PMID 40891102, 2025).
pancreatic adenocarcinoma (1 paper, 2024). "Comprehensive analysis, together with the pancreatic adenocarcinoma (PAAD) dataset from The Cancer Genome Atlas (TCGA), revealed that the ANTXR1, CMTM6, ITGB6, PIGR, and PTGS2 genes were significantly upregulated in GEM‐resistant PDAC cell lines." (PMID 39488785, 2024).
periodontitis (1 paper, 2012). An acute or chronic inflammatory process that affects the tissues that surround and support the teeth. "Whilst the expression of pIgR, Arp 3, CA VI and IL-1Ra was down-regulated, PLS-2, LEI and IGJ chain appeared to be up-regulated in the saliva of the T2DM patients with periodontitis compared to the controls." (PMID 22606001, 2012).
pneumococcal pneumonia (1 paper, 2017). A febrile disease caused by STREPTOCOCCUS PNEUMONIAE. "Finally, we could link increased pIgR-mediated SIg transepithelial transport to augmented pneumococcal binding by IgA and IgM coinciding with augmented host protection during pneumococcal pneumonia." (PMID 28694492, 2017).
prostate carcinoma (1 paper, 2022). A carcinoma that arises from epithelial cells of the prostate gland. "While we did not detect a separate hillock cell population within our prostate cancer epithelial cells, we did detect a distinct population representing 6.5% of all epithelial cells (872 of 13,322) characterized by expression of PIGR, MMP7, CP, and LTF (FDR q < 10e-20)." (PMID 35013146, 2022).
renal oncocytoma (1 paper, 2024). "Expression of biomarkers MAPRE3, ADGRF5, and GPNMB differentiates renal oncocytoma from chromophobe RCC, and PIGR and SOSTDC1 distinguish papillary RCC from MTSCC." (PMID 38703764, 2024).
serous carcinomas (1 paper, 2014). "PIGR expression was significantly lower in serous compared to non-serous carcinomas (p <0.001)." (PMID 24568264, 2014).
Sjogren syndrome (1 paper, 2022). An autoimmune disorder in which immune cells attack and destroy the glands that produce tears and saliva. "A reduction in the level of the polymeric immunoglobulin receptor (pIgR), a protein that regulates the concentration of secretory immunoglobulin A, appears to be specific to Sjogren’s syndrome." (PMID 36293921, 2022).
Splenomegaly (1 paper, 2018). Abnormal increased size of the spleen. "Remarkably, WTs challenged orally with S. Typhimurium exhibited increased splenomegaly, tissue colonization, and pro-inflammatory cytokines vs. pIgR KOs, which showed increased survival following either oral or IV infection." (PMID 29856838, 2018). "Similarly, pIgR KO mice were found to be protected from splenomegaly and reduction in cecum weight, two known sequelae of S. Typhimurium infection, relative to C57BL/6." (PMID 29856838, 2018).
Usher syndrome (1 paper, 2015). A syndromic diseae characterized by the association of sensorineural deafness (usually congenital) with retinitis pigmentosa and progressive vision loss. "Twelve SNPs were associated with factor 2 (LCDA) levels in any race, with only two of them showing more than nominal significance in the validation cohort (rs12129555 just downstream from polymeric immunoglobulin receptor [PIGR] and rs17025690 in Usher syndrome 2A [USH2a])." (PMID 26540294, 2015).
vitamin A deficiency (1 paper, 2023). Deficiency of vitamin A due to malnutrition, malabsorption, or dietary lack. "Vitamin A deficiency affects pIgR and RARα expression levels in vivo and in vitro." (PMID 37180172, 2023).
tumor (65 papers, 2003 to 2026). "IgA can be transported into the tumor microenvironment via PIGR-mediated mechanisms, where it specifically recognizes and expels mutated oncogenic proteins in cells, thereby inhibiting tumor growth." (PMID 40386563, 2025). "Two genes identified in HG3 tumor epithelial cells are broadly implicated in many cancers with worse prognoses, PIGR and AGR2." (PMID 30383866, 2018). "Non-parametric tests were applied to explore associations between PIGR expression in primary tumours and clinicopathological characteristics." (PMID 24694107, 2014). "There were also significant inverse associations between pIgR expression and perineural invasion (p = 0.027), tumour differentiation (p<0.001) and lymphatic (p = 0.016), vascular (p = 0.033) and peripancreatic fat growth (p = 0.039)." (PMID 25397670, 2014). "A borderline significant association of increasing pIgR expression and an improved survival was seen for pancreatobiliary type tumours." (PMID 25397670, 2014). "PIgR expression was significantly associated with tumour origin (p = 0.033), with the highest expression in tumours of duodenal origin, and the lowest expression in tumours of pancreatic origin." (PMID 25397670, 2014). "High tumour-specific expression of PIGR was found to be associated with a favourable prognosis in unadjusted, but not in adjusted, analysis." (PMID 24568264, 2014). "Reduced PIGR expression in primary tumours was significantly associated with more advanced tumour stage (p = 0.002) and inversely associated with involved margins (p = 0.034)." (PMID 24694107, 2014). "In cases with radically resected (R0) primary tumours there was a significant association between high PIGR expression and a prolonged OS (p = 0.030)." (PMID 24694107, 2014). "Similarly, high tumor-specific expression of PIGR is associated with a favorable prognosis in epithelial ovarian cancer (EOC)." (PMID 40386563, 2025). "We identified several spatial biomarkers linked to non-recurrence, including elevated NKG7 expression in CD45+ immune cell regions (p = 0.0011) and higher TFPI2 and PIGR expression in tumor areas (p = 2.09 × 10−6), both associated with improved progression-free survival." (PMID 40422184, 2025). "In addition, aberrant methylation of PIGR was closely associated with distant metastasis (P = 0.005), tumor stage (P = 0.039) and OS status (P = 0.021)." (PMID 35992840, 2022). "Nowadays, the roles of aberrant PIGR in tumors remain controversial, which might be due to the tumor heterogeneity or the different underlying mechanisms." (PMID 36157233, 2022). "Analyses of the association of continuous pIgR expression with survival were however confirmatory, and, in the case of pancreatobiliary type tumours, an even stronger, although only borderline significant, association between high pIgR expression and a prolonged survival was observed." (PMID 25397670, 2014). "Associations of pIgR expression in primary tumours with clinicopathological parameters." (PMID 25397670, 2014). "Thus, an inhibitory effect of MMP-2 by SC could be a possible explanation for the favourable outcome associated with a high tumour-specific PIGR expression." (PMID 24694107, 2014). "Conversely, gene expressions previously linked to tumor cell differentiation and favorable outcome, such as SLC26A3, PIGR, CKB and FABP1, were highly expressed in GPA33-high cancer cells." (PMID 39472498, 2025). "In endometrial cancer, the binding of IgA to pIgR activate inflammatory pathways within tumor cells, enhancing immune recognition and survival of tumor cells." (PMID 41357192, 2025). "We identified the expression of NKG7 by immune cells, as well as TFPI2 and PIGR in the tumor area, as potential biomarkers that predict recurrence and survival of patients with HGSC." (PMID 40422184, 2025). "To explore the relationship between changes in PIGR expression and the tumor microenvironment, we conducted immune cell infiltration analysis and immune-related signatures analysis." (PMID 40386563, 2025).
tumor (continued). "In ovarian cancer, IgA has been detected on tumor cells co-localized with the pIgR, facilitating IgA transcytosis and sensitizing tumor cells to cytotoxic T cell-mediated killing." (PMID 41357192, 2025). "IgA also activates inflammatory pathways within tumor cells by binding to pIgR in some tumor types, promoting tumor cell growth and survival." (PMID 41357192, 2025). "We further confirmed this association by examining the expression of CD3 and CD20 in tumor tissues with low and high PIGR expression." (PMID 40386563, 2025). "For example, research has found that the exosome proteins LG3BP and PIGR play a key role in tumor transformation, invasion, and proliferation, while being closely associated with poor prognosis in patients." (PMID 40433362, 2025). "We also explored the impact of PIGR expression on tumor cell behavior and preliminarily verified that this impact is associated with tumor immunity." (PMID 40386563, 2025). "The polymeric immunoglobulin receptor (pIgR) mediated IgA transcytosis also contributed to the tumor control, as pIgR knockout reduced BDNF and TSPAN7 IgA mediated tumor control." (PMID 40356924, 2025). "The E285K-mAbs were also produced in the dimeric IgA (dIgA) format, whose anti-tumor activity depended on the polymeric immunoglobulin receptor (PIGR), a membrane Ig receptor, whereas that of IgG1 relied on TRIM21, an intracellular IgG receptor." (PMID 38886748, 2024). "Recognition of dIgA by PIGR leads to transcytosis, allowing the PIGR-dIgA complex to enter the tumor cells, where KrasG12D is neutralized and expelled." (PMID 38886748, 2024). "Of the 13 validated differentially expressed genes, 7 and 6 were consistently identified by both technologies as significantly more highly expressed in the P5.1/PIGR+ or P5.2/PTGS1+ tumour subclones, respectively." (PMID 38570491, 2024). "On the other hand, pRCC showed upregulation of TFPI2, FSTL1, FAS, and PIGR in the epithelial/tumor, C1QTNF3 and GRN in the endothelial, and ITGAX, HLA-DQA1, IL4I1, and CTSC in the immune compartments." (PMID 38703764, 2024). "dIgA promotes the presentation of intracellular neoantigen through PIGR expressed on the tumor cell surface." (PMID 38886748, 2024). "dIgAs against KRASG12D and IDH1R132H promote antigen expulsion from the cytosol of PIGR+ tumor cells and impede tumor growth." (PMID 38886748, 2024). "To enhance our insights into the prognostic validity of the five-gene signature, we examined the expression of ATP6AP1, SLC7A5, EPDR1, SDC1, and PIGR in 13 paired BC samples, comparing them with their adjacent non-tumor tissues through RT-PCR." (PMID 38162504, 2023). "In settings with high levels of complement components, IgG1 can also play a protumor role, while IgA can activate CD8+ T cells by binding to pIgR in tumor cells." (PMID 37138324, 2023). "In the tumor tissues of nude mice after CAFs-Exo injection (P < 0.0001) and in Cal-27 tumor cells co-cultured with CAFs-Exo (P < 0.0001), the expression of PIGR was significantly higher than that in the NC group." (PMID 37365497, 2023). "Consistent with the results of the proliferation assay in vitro, we found that PIGR in RKO cells significantly inhibited tumor growth." (PMID 35992840, 2022). "Our study showed that the differences between CRC and adjacent normal tissues in methylation, mRNA and protein expression were significant and that PIGR methylation and expression varied with the tumor stage." (PMID 35992840, 2022). "To define the role of pIgR-mediated IgA transcytosis in anti-tumour activity, we challenged RAG1-deficient mice with PIGR-ablated OVCAR3 tumours." (PMID 33536615, 2021). "In line with previous reports 10, 13, we found that PIGR was upregulated in tumor tissues and serum samples in HCC patients." (PMID 33390805, 2021). "Recent studies have demonstrated that tumor-derived IgA abrogates tumor growth through antigen-dependent redirection of Fcα/μ+ myeloid cells and antigen-independent, pIgR-mediated transcytosis." (PMID 34868013, 2021).